PTPN22 (protein tyrosine phosphatase non-receptor type 22)
Diseases named in the same sentence as PTPN22 in open-access papers (continued):
Sharing a sentence is not in itself a finding about the gene and the disease.
autoimmune disease (continued). "PTPN22 has four proline-rich motifs (P1-P4) at the C-terminus, and the P1 motif interacts with the SH3 domain of CSK; rs2476601 (GRCh38 NC_000001.10:g.114377568A>G) is located in the P1 motif of PTPN22; rs2476601 is associated with more than ten autoimmune diseases, including T1D." (PMID 37240014, 2023). "Mutations of PTPN22 have been associated with a range of autoimmune diseases including T1D." (PMID 37334284, 2023). "Changes in PTPN22 may affect both the quantity and quality of the T cell immune response, and may increase the risk of autoimmune diseases." (PMID 35967336, 2022). "For example, polymorphisms in PTPN22 (Protein tyrosine phosphatase, non-receptor type 22) which are known to be associated with HT and other autoimmune disorders cause altered Ca2+ flux upon BCR ligation and B cell-restricted expression of risk variants is enough to initiate autoimmunity." (PMID 36389812, 2022). "Summary of the PTPN22 C1858T polymorphism with different types of autoimmune diseases." (PMID 36013501, 2022). "Although it is not clear whether the SNP is a gain-of-function or loss-of-function variant, studies of animal models suggest a gain-of-function for the PTPN22 variant in the development of autoimmune diseases." (PMID 36220996, 2022). "Further, epidemiological studies confirm that the functional C1858T PTPN22 SNP is associated with susceptibility to several autoimmune diseases both organ-specific (T1D) and systemic [RA and systemic lupus erythematosus (SLE)] in different populations and that its prevalence is ethnicity-dependent." (PMID 35355982, 2022). "Variations in PTPN22 are associated with various autoimmune disorders, including AITD." (PMID 33746952, 2021). "Notably, a single nucleotide polymorphism in PTPN22 gene, encoding a tryptophan at amino acid 620, has been described as a susceptibility locus for autoimmune diseases and infections." (PMID 33494775, 2021). "PTPN22 620W variation causes the substitution of arginine with tryptophan at amino acid residue 620, disturbing the function of PTPN22, which is involved in B-cell receptor and T cell receptor signaling, causing autoimmune diseases." (PMID 33841406, 2021). "Additionally, we tend to claim that population with PTPN22-C1858T is more likely to gain autoimmune disease and the diseases itself carry a high risk of various infection." (PMID 33717071, 2021). "PTPN22 is a known immune regulator gene and this particular variant (rs2476601 A allele) has been associated with an increased risk of several autoimmune diseases, including rheumatoid arthritis, systemic lupus erythematosus, vitiligo, autoimmune thyroid conditions, type 1 diabetes, and others." (PMID 34145262, 2021). "After the HLA system, PTPN22 polymorphisms may be the most important genetic risk factor for autoimmune diseases." (PMID 33746952, 2021). "Thus, the PTPN22 1858T polymorphism is considered as one of the prominent risk factors for autoimmune diseases outside the Human leukocyte antigen locus." (PMID 34805727, 2021). "We provided evidence that the C1858T PTPN22 gene polymorphism could be a relevant target for immunomodulation in the treatment of C1858T patients affected by an autoimmune disease, that is, T1D." (PMID 35008834, 2021). "Moreover, genome-wide association studies showed a correlation between PTPN22-C1858T polymorphism and increased risk of autoimmune diseases as well as bacterial infections." (PMID 33717071, 2021). "The lead SNP on chr1, rs6679677, is in high LD (r2 = 0.96) with a non-synonymous variant in exon 12 of the PTPN22 gene, a well-described genetic risk variant for autoimmune diseases (rs2476601, p = 2.82 × 10−24) (these are also the only two variants in the credible set)." (PMID 34145262, 2021).
autoimmune disease (continued). "Regarding its contribution to disease, a C1858T single nucleotide polymorphism within PTPN22 (encoding R620W) is one of the strongest genetic risk factors outside the HLA for the development of multiple autoimmune diseases, including rheumatoid arthritis, type I diabetes, and lupus." (PMID 32194571, 2020). "PTPN22 is a coding gene for a protein involved in the responsiveness of B and T lymphocyte receptors, whose mutations may be responsible for the onset of autoimmune diseases." (PMID 32143537, 2020). "A single point mutation in the human PTPN22 gene is associated with a higher risk for several autoimmune diseases such as rheumatoid arthritis, type 1 diabetes, systemic lupus erythematosus among others and is the strongest non-HLA risk factor described to date." (PMID 32047502, 2020). "Autoimmune diseases affecting connective tissues, joints, muscles, blood, pancreas, kidney or thyroid show a stronger association with PTPN22 than diseases of the gastrointestinal tract or immune-privileged sites, such as the central nervous system and the eye." (PMID 30871019, 2019). "The PTPN22 rs2476601 (p.Arg620Trp) polymorphism has been linked to several autoimmune diseases." (PMID 30915320, 2019). "The PTPN22 (R620W) SNP was first reported to be associated with type 1 diabetes and later with rheumatoid arthritis, systemic lupus erythematosus, autoimmune thyroid disease and as such with several other autoimmune diseases." (PMID 30384859, 2018). "Carriage of the PTPN22 risk allele is associated with increased susceptibility to major autoimmune disorders such as diabetes, thyroid syndromes, rheumatoid arthritis, systemic lupus erythematosus, and myasthenia gravis, as well as with altered host responses to bacterial and fungal infections." (PMID 28723925, 2017). "Moreover, our findings add to the existing evidence that PTPN22 is an important genetic risk factor for different autoimmune diseases." (PMID 27215233, 2017). "The findings of this study together with those of other studies propose that the +1858C/T PTPN22 SNP predisposes individuals to autoimmune diseases because of enhanced suppression of T-cell receptor signaling during thymic development, which allows the survival of auto-reactive T-cells." (PMID 27215233, 2017). "rs2476601 in PTPN22 was a missense single nucleotide polymorphism (SNP), which has been more studied previously, and has been reported associations with some types of autoimmune diseases, including RA and SLE." (PMID 28977835, 2017). "Furthermore, three loci which previously have been implicated in JIA and several other autoimmune diseases – the PTPN22 locus on 1p13, the IL2RA locus on 10p15, and the ANTXR2 locus on 4q21.21 – were nominally associated with JIA." (PMID 27005825, 2016). "Recent studies on PTPN22 knockout mice suggested that the increase risk of developing autoimmune diseases could occur through alterations of the periphery Treg cells while PTPN22 knockout increases the thymic selection of Treg cells." (PMID 26734582, 2015). "Given the strong association of Ptpn22 in several human autoimmune diseases, identifying nuclear substrates of Ptpn22 may shed light on the pathogenesis of those diseases." (PMID 25993510, 2015). "Furthermore, a wealth of data has accumulated in the past decade identifying PTPN22 single-nucleotide polymorphisms (SNPs) as risk factors for the development of autoimmune diseases such as rheumatoid arthritis, type 1 diabetes and lupus (reviewed in 8)." (PMID 25715232, 2015). "Moreover, mutations in PTPN22 have been reported in a variety of other autoimmune diseases, including SLE, rheumatoid arthritis, and type 1 diabetes." (PMID 25569146, 2015). "Previous studies found that PTPN22 mutation may promote T cell activation and thus induce autoimmune diseases." (PMID 25781893, 2015). "Several genome-wide association studies have linked PTPN22 to autoimmune diseases." (PMID 24433447, 2014).
autoimmune disease (continued). "The identified association between the PTPN22 1858C>T gene polymorphism and T cell activation suggests that it may contribute to development of autoimmune diseases." (PMID 24985973, 2014). "In these latter populations it is possible that SNPs that are in linkage disequilibrium with the 1858C/T SNP (rs2476601) or even other functional variants of PTPN22 might be involved in the pathogenesis of autoimmune disease." (PMID 24816862, 2014). "Several studies showed that splice variants of PTPN22 rs2476601 may associated with type 1 diabetes and other autoimmune diseases." (PMID 25005490, 2014). "The rs2476601 PTPN22 SNP is linked with several autoimmune diseases." (PMID 25452756, 2014). "Taking into account the fact that autoimmune diseases accumulate in individuals and families, we studied the possibility of association of PTPN22 C1858TT polymorphism with personal history of HT and family history of T1DM without positive results in the study population." (PMID 23936838, 2013). "The purpose of the present study was to investigate the frequency of the PTPN22 +1858 C/T single nucleotide polymorphism (SNP) (rs 2476601), previously shown to be associated with several autoimmune diseases, in patients with psoriatic arthritis (PsA) in comparison with population based controls." (PMID 21410964, 2011). "In many autoimmune diseases PTPN22 represents the second most strongly associated locus after HLA." (PMID 22654555, 2011). "The single nucleotide polymorphism (SNP) rs2476601 (+1858C/T), located in exon 14 of the PTPN22 gene, has previously been found associated with several autoimmune diseases, for example, diabetes type-I and RA, with a stronger association with ACPA sero-positive RA." (PMID 21410964, 2011). "In conclusion, this study shows that the +1858T allele in the PTPN22 gene, previously shown to be associated with several autoimmune diseases, is also associated with PsA in patients from northern Sweden, a result that is consistent with previous data regarding a population from Toronto." (PMID 21410964, 2011). "One of the best known examples is the allelic variant of the lymphoid tyrosine phosphatase LYP (PTPN22) which is associated with multiple autoimmune diseases, including systemic lupus erythematosus, rheumatoid arthritis, type 1 diabetes, and autoimmune thyroid disease." (PMID 21044313, 2010). "Recently, it was reported the single nucleotide polymorphism (SNP), R620W (rs2476601), in PTPN22 increased susceptibility to several autoimmune diseases including rheumatoid arthritis (RA), systemic lupus erythematosus (SLE), and insulin dependent diabetes mellitus (IDDM)." (PMID 19503742, 2009). "Recent evidence has also implicated the common allele of the R620W single-nucleotide polymorphism (SNP) (rs2476601) in the hematopoietic-specific protein tyrosine kinase, protein tyrosine phosphatase N22 (PTPN22), with susceptibility to several autoimmune diseases, including RA." (PMID 17665434, 2007). "Since genetic interactions between HLA and non-HLA loci have been described for susceptibility to RA and other autoimmune diseases, genotype distributions for the PTPN22 1858T SNP in subgroups stratified according to the number of HLA-DRB1 SE alleles were determined and compared to controls." (PMID 16635271, 2006). "This could suggest that the PTPN22 T variant influences the progression of overt autoimmune disease once autoantibodies, such as anti-CCP antibodies, have developed." (PMID 16507117, 2006). "Indeed, the known T1D susceptibility loci follow this observation: while both CTLA4 and PTPN22 loci are associated with several autoimmune diseases, the insulin VNTR locus is likely to be T1D-specific rather than a general autoimmune locus." (PMID 16519819, 2006).
autoimmune disease (continued). "Similarly, a functional polymorphism in the protein tyrosine phosphatase gene, the PTPN22 620 W allele, has been recognized as a predisposing factor for several autoimmune diseases including Graves and Hashimoto thyroid diseases the same as for GPA and ANCA positivity." (PMID 38914775, 2024). "Although we accept that the difference between WT and Ptpn22 variant cDC2 populations may appear modest, over the lifetime of a human, these changes could have significant functional impact over the decades that precede autoimmune disease onset." (PMID 32194571, 2020). "Considering that some of the strongest associations of the PTPN22 1858C/T are with autoimmune diseases characterized by the production of circulating autoantibodies, dysregulation of B-cell clonal deletion and receptor editing is likely to contribute to PTPN22-associated autoimmune diseases." (PMID 30871019, 2019). "Of note PTPN22 c.1858C>T variant leading to p.Arg620Trp substitution (rs2476601) showed association pattern with target tissue specificity being less involved in pathogenesis of autoimmune diseases triggered by environmental factors primarily acting on target tissues such as gut mucosa." (PMID 30915320, 2019). "Given the link between PTPN22R620W and autoantibody associated autoimmune diseases, and the regulation of FcRs by Src and Syk family kinases, we set out to investigate if PTPN22 regulates FcγR dependent immune complex uptake and activation in DCs and whether this can alter T cell effector responses." (PMID 30139951, 2018). "PTPN22 gene could play a crucial role in people’s susceptibility to certain autoimmune diseases." (PMID 27215233, 2017). "Mutation of PTPN22 gene may potentiate T cell activation and induce autoimmune diseases." (PMID 25005490, 2014). "Association between PTPN22 620W polymorphism and GD has been demonstrated in numerous studies among Caucasians with strength typically estimated as OR 1.5-1.9, which makes this variant one of the strongest known genetic factors predisposing to autoimmune diseases." (PMID 22654555, 2011). "In concordance with a previous data establishing PTPN22 1858 C/T SNP association with several autoimmune diseases, our findings provide further evidence that the PTPN22 gene may play an important role in the susceptibility to some autoimmune diseases." (PMID 21467606, 2011). "According to the available data on PTPN22 allele frequencies distribution worldwide, the degree of the association between 1858C/T SNP and different autoimmune diseases is variable among ethnic populations, suggesting that 1858C/T SNP may be of little importance for RA in Russian population." (PMID 21467606, 2011). "Recent research has primarily focused on PTPN22's role in autoimmune diseases and immune cells, with limited understanding of its function in tumor cells 23-25." (PMID 41522360, 2026). "Despite the critical role of PTPN22 in T cell biology and autoimmune diseases, its regulatory mechanisms during TCR signaling and disease progression remain inadequately understood." (PMID 40911684, 2025). "As cardiovascular diseases are the most common complications in RA patients, the inhibition of PTPN22 represents a potential therapeutic target for autoimmune diseases such as RA and its complications." (PMID 40305360, 2025). "Cell-type-specific deletion of PTPN22 in mice is warranted to further elucidate its role in regulating autoimmune disorders." (PMID 39944077, 2025). "The inhibition of PTPN22 by quercetin opens new possibilities for developing quercetin-based therapies for cancer and autoimmune diseases." (PMID 39451542, 2024). "For example, protein tyrosine phosphatase non-receptor type 22 (PTPN22), a gene that negatively regulates T cell activation, is associated with many autoimmune diseases but in opposite directions." (PMID 38796637, 2024). "As a multifunctional regulator of immune cells, PTPN22 is a key player in multiple human autoimmune diseases and response to infection." (PMID 38777143, 2024).
autoimmune disease (continued). "Our study provides a theoretical basis for understanding the relationship between the enzyme activity of PTPN22 and autoimmune diseases." (PMID 37833951, 2023). "SNPS in genes: PADI4 (rs2240340), STAT4 (rs7574865), CD40 (rs4810485), PTPN22 (rs2476601), and TRAF1 (rs3761847) have been described as risk factors for the development of autoimmune diseases, including RA." (PMID 37108746, 2023). "The substantial role of PTPN22 and Mpro makes it an attractive target for developing anti-autoimmune disorders and SARS-CoV-2 agents." (PMID 37771457, 2023). "Accordingly, PTPN22 expression has been studied in different autoimmune diseases, such as inflammatory bowel disease, rheumatoid arthritis, and SLE with diverse results." (PMID 36428917, 2022). "To sum up, we can conclude that the SNPs of PTPN22 play an important role in the onset of autoimmune diseases including T1DM, RA, JIA, PsA, SLE, SSc, AITD, and different forms of vasculitis." (PMID 36013501, 2022). "Such is the case for protein tyrosine phosphatase, non-receptor type 22 (PTPN22), which is strongly associated with many autoimmune diseases." (PMID 34508276, 2022). "Candidate gene mapping involving variant annotation, finemapping, and colocalisation analyses, and data from mouse models highlights the involvement of genes with a known role in autoimmune disease (PTPN22, HLA, IL2RA, and AIRE)." (PMID 34145262, 2021). "There is evidence that many of the susceptibility genes are shared by various autoimmune diseases, such as CTLA4 and PTPN22, which indicate that autoimmune diseases have some similar genetic and molecular pathways." (PMID 34238277, 2021). "The PTPN22, CTLA4, and BACH2 loci are well-known drivers of autoimmune disease and we identified the variants and haplotype blocks that have previously been described in AAD and common autoimmune comorbidities." (PMID 33574239, 2021). "Roles of PTPN22-C1858T in infection and prevention mainly are beneficial to the patients with autoimmune diseases." (PMID 33717071, 2021). "The PTPN22 gene encodes lymphoid tyrosine phosphatase (LYP) protein, which has been associated with several autoimmune diseases." (PMID 34735462, 2021). "Among these, PTPN22 encodes a negative regulator of T-cell receptor (TCR), which has been associated with human autoimmune diseases, bovine leukemia virus, and milk somatic cell counts of cow." (PMID 32083286, 2020). "The protein tyrosine phosphatase non-receptor type 22 gene (PTPN22) variants have been identified of association with JIA and many other autoimmune diseases." (PMID 33076506, 2020). "Polymorphisms in the protein tyrosine phosphatase, non-receptor type 22 (PTPN22) is associated with increased susceptibility to T1D and other autoimmune diseases." (PMID 33603744, 2020). "We analyzed a cohort of 305 ME/CFS patients and 201 healthy controls for potential disease association of the PTPN22, CTLA4, TNF, and IRF5 SNPs that were described to be risk loci for various autoimmune diseases." (PMID 32328064, 2020). "Both, the PTPN22 rs2476601 and CTLA4 rs3087243 SNPs were shown to be associated with numerous autoimmune diseases, including T1D, SLE, and RA." (PMID 32328064, 2020). "The 1858T allele in the protein tyrosine phosphatase non-receptor type 22 (PTPN22) locus shows one of the strongest and most consistent genetic associations with autoimmune diseases." (PMID 30871019, 2019). "Consistent with a role of LYP in preventing autoimmunity, a SNP in PTPN22 human gene, which results in the LYP mutant R620W, confers increased risk to several autoimmune disorders, including RA, SLE, and Type 1 diabetes (T1D)." (PMID 31297117, 2019). "The 1858T allele in the protein tyrosine phosphatase non-receptor type 22 (PTPN22) locus has a strong and consistent genetic association with autoimmune diseases." (PMID 30871019, 2019).